FH (fumarate hydratase)
Diseases named in the same sentence as FH in open-access papers (continued):
Sharing a sentence is not in itself a finding about the gene and the disease.
hereditary leiomyomatosis and renal cell cancer (continued). "Germline mutations of FH, the gene that encodes for the tricarboxylic acid TCA (TCA) cycle enzyme fumarate hydratase, are associated with an inherited form of cancer referred to as Hereditary Leiomyomatosis and Renal Cell Cancer (HLRCC)." (PMID 21695080, 2011). "A recent study showed that the synthetic lethal (negative epistasis) relationship between fumarate hydratase and haem oxygenase can be employed successfully to identify an in vitro drug target in hereditary leiomyomatosis and renal-cell cancer (HLRCC) cells." (PMID 25625594, 2015). "Indeed, the SDH and FH genes have been demonstrated to be tumour suppressor genes (TSG) via this pseudohypoxic drive in paraganglioma, hereditary leiomyomatosis and renal cell carcinomas." (PMID 19778456, 2009). "Despite its essential role in central carbon metabolism, FH is inactive or absent in several tumors, such as hereditary leiomyomatosis and renal cell cancer (HLRCC)." (PMID 36428601, 2022).
renal cell carcinoma (187 papers, 2005 to 2026). "Fumarate hydratase (FH)-deficient renal cell carcinoma (RCC) can exhibit striking histologic and immunophenotypic heterogeneity." (PMID 42317258, 2026). "Histopathological examination revealed metastatic fumarate hydratase-deficient renal cell carcinoma associated with uterine leiomyomatosis with R1 resection margin at IVC." (PMID 41789002, 2026). "Fumarate hydratase (FH)-deficient renal cell carcinoma is an aggressive neoplasm driven by inactivating mutations of the FH gene, which cause metabolites like S-(2-succinyl)cysteine (2SC) to accumulate and trigger cascades supporting malignant transformation." (PMID 39899047, 2025). "The FH cancer susceptibility gene also had three concordant P/LPGVs, with one each in brain, renal, and upper GI cancers, with just renal cell carcinoma being a common phenotype." (PMID 41465149, 2025). "Summary of clinical and pathological features of cases with eosinophilic globules in fumarate hydratase-deficient renal cell carcinoma." (PMID 40678055, 2025). "Eleven FH-deficient renal cell carcinomas, including primary neoplasms and metastases, were retrieved and evaluated for clinical-pathological features and immunohistochemical expression of FH, 2SC (commercially available), and STING." (PMID 39899047, 2025). "Background/Objectives: Fumarate hydratase-deficient leiomyomas (dFH-LMs) are a rare subtype of uterine smooth muscle tumors (USMTs) with implications for hereditary leiomatosis and renal cell carcinoma (HLRCC)." (PMID 41374387, 2025). "Fumarate hydratase deficiency-associated renal cell carcinoma (FH-RCC) is a rare, aggressive subtype of renal cell carcinoma (RCC) driven by FH gene mutations." (PMID 40678055, 2025). "Fumarate hydratase deficiency-associated renal cell carcinoma (FH-RCC) is an infrequent subtype of renal cell carcinoma (RCC) resulting from germline or somatic mutations in the FH gene." (PMID 40678055, 2025). "Patients with FH deficiency are particularly prone to developing benign disease, such as leiomyomas (in the skin and uterus), as well as malignancies, such as renal cell carcinoma (RCC)." (PMID 40002168, 2025). "Deployment of these findings on the case-study protein fumarate hydratase (FH), associated with renal cell cancer, corroborated the marked enrichment of CpDAAs proximal to both pathogenic and VUS, both in linear sequence and 3D space." (PMID 40412387, 2025). "Previously, FH-deficient renal cell carcinoma was usually recognized as a highly aggressive tumor, prone to local progression and early metastasis, with a poor prognosis." (PMID 39659780, 2024). "This is because there is abundant CD8+T cell infiltration in fumarate hydratase-deficient renal cell carcinoma, and the depletion of T cells is related to poor immune efficacy in FH-dRCC patients." (PMID 38376408, 2024). "A case of low-grade FH-deficient renal cell carcinoma in a male is reported, and its clinicopathological features were analyzed and literature review was performed." (PMID 39659780, 2024). "Germline mutations in the FH gene can cause autosomal dominant tumor syndromes with characteristic lesions manifesting as skin and uterine leiomyomatosis and renal cell carcinoma." (PMID 39659780, 2024). "FH-RCC is a rare subtype of renal cell carcinoma characterized by mutations and functional defects in the FH gene." (PMID 39555225, 2024). "The ever-expanding histologic picture of FH-deficient renal cell carcinoma has further increased the difficulty of diagnosing this disease, and in practice, it needs to be differentiated from more types of renal tumors." (PMID 39659780, 2024). "Subsequently, in February 2023, following the diagnosis of FH-deficient renal cell carcinoma, the patient’s treatment regimen was adjusted." (PMID 38974045, 2024). "Fh-d RCC is a clinical manifestation of skin and/or uterine leiomyoma and renal cell carcinoma caused by FH gene mutation (system/germ line), and has familial heritability." (PMID 39957804, 2024).
renal cell carcinoma (continued). "In HLRCC syndrome, FH-deficient renal cell carcinomas typically present as aggressive, unilateral, and often-cystic masses with heterogeneous enhancement." (PMID 39282017, 2024). "Integrating the genetic testing and pathological findings, the patient was diagnosed with FH genotype-deficient renal cell carcinoma." (PMID 38974045, 2024). "We report a case of low-grade FH-deficient renal cell carcinoma in a middle-aged male and conduct a literature review to improve the understanding of the diagnosis and management of rare cases of this tumor in pure low-grade form." (PMID 39659780, 2024). "Immunohistochemistry (IHC) is used to detect the deletion of FH expression in tumor cells to diagnose FH-deficient renal cell carcinoma, which has been proved to be closely related to the inactivation mutation of the FH gene." (PMID 38974045, 2024). "Hereditary leiomyomatosis and renal cell carcinoma (HLRCC) is a kind of hereditary disease caused by germline mutation of fumarate hydratase (FH) gene, which is manifested as renal malignant tumor of skin and uterine smooth muscle myoma." (PMID 38974045, 2024). "The FH-deficient renal cell carcinoma exhibits a range of architectural features, including papillary, solid, tubulocystic, and cribriform, when observed under a microscope." (PMID 38765391, 2024). "Given the hereditary nature of FH gene-deficient renal cell carcinoma, whole exon gene sequencing was conducted on peripheral blood samples from the patient’s mother and two daughters." (PMID 38974045, 2024). "FH-deficient Renal Cell Carcinoma (FH-deficient RCC) are inherited tumors caused by mutations in the fumarate hydratase (FH) gene, which plays a role in the tricarboxylic acid cycle." (PMID 38974045, 2024). "Here, we present a case of renal cell carcinoma deficient in FH in a 43-year-old woman, who harbored a novel heterozygous variant in the sixth exon of the FH gene (c.799_803del, c.781_796del)." (PMID 38974045, 2024). "Fumarate hydratase (FH) deficient renal cell carcinoma (RCC) is a type of tumor with definite metabolic disorder, but the mechanism of metabolic remodeling is still unclear." (PMID 38374146, 2024). "Fumarate hydratase-deficient renal cell carcinoma (FH-deficient RCC) is a rare type of renal cell carcinoma (RCC) caused by alterations in the fumarate hydratase (FH) gene." (PMID 39659780, 2024). "For instance, the presence of clear cell renal carcinoma with sarcomatoid transformation and FH-deficient renal cell cancer has been reported." (PMID 38765391, 2024). "Fumarate hydratase-deficient renal cell carcinoma is a rare pathological subtype caused by a pathogenic mutation in the fumarate hydratase gene located in 1q42.3-q43 and was defined by the World Health Organization (WHO 5th edition) in 2022." (PMID 37076922, 2023). "The gene mutation of FH was the driving cause of hereditary leiomyomatosis and renal cell carcinoma (HLRCC)." (PMID 37427096, 2023). "This proposed mechanism explains how FH mutations can increase the risk of developing leiomyomas of the uterus or skin, uterine leiomyosarcoma, and renal cell carcinoma." (PMID 37663422, 2023). "Patients with HLRCC develop cutaneous and uterine leiomyomas as well as FH-deficient renal cell carcinomas (RCCs)." (PMID 37259915, 2023). "We also estimated the cellular composition of bulk RNA-sequencing datasets of FH-deficient renal cell carcinomas (RCCs), SDH-deficient RCCs and common RCC subtypes from The Cancer Genome Atlas (TCGA) by deconvolution of the transcriptomics data." (PMID 36890229, 2023). "Fumarate hydratase-deficient renal cell carcinoma is a rare pathological subtype that was defined by the World Health Organization (WHO 5th edition) in 2022." (PMID 37076922, 2023). "We compared NMR and LC-MS/MS analysis of tumors from two kidney cancer patients with FH deficient renal cell carcinoma (FHdRCC)." (PMID 37611583, 2023).
renal cell carcinoma (continued). "Fumarate hydratase–deficient (FH-deficient) renal cell carcinoma (RCC) represents a particularly aggressive form of kidney cancer." (PMID 37259915, 2023). "The median relapse-free survival for patients with FH gene mutation was only 9 months, so the 2022 WHO classification of renal cell carcinoma has changed the term from HLRCC to FH-deficient RCC which represents a new subtype in nccRCC." (PMID 37427096, 2023). "Fumarate hydratase-deficient renal cell carcinoma is a very rare renal tumor that is defined on a molecular basis." (PMID 37076922, 2023). "It has been widely reported that FH is closely associated with the development of various tumors, such as uterine smooth muscle tumors, renal cell carcinoma, pancreatic cancer, gastric cancer, and lung cancer." (PMID 38139831, 2023). "The incidence of fumarate hydratase-deficient renal cell carcinoma is rare in Asian populations, especially in Chinese populations." (PMID 37076922, 2023). "Molecular knowledge has allowed the identification of some other specific subtypes, such as fumarate hydratase–deficient renal cell carcinoma (RCC) or succinate dehydrogenase–associated RCC." (PMID 36816976, 2023). "Germline or somatic loss-of-function mutations of fumarate hydratase (FH) predispose patients to an aggressive form of renal cell carcinoma (RCC)." (PMID 37053010, 2023). "Fumarate hydratase–deficient renal cell carcinoma (FH-RCC) is a rare highly aggressive subtype of kidney cancer for which the distinct genomic, transcriptomic, and evolutionary relationships between metastatic and primary lesions are still unclear." (PMID 37131267, 2023). "Chromosomal genetic disorders, such as von Hippel Lindau (VHL) syndrome with VHL gene mutation and hereditary leiomyomatosis and renal cell cancer with fumarate hydratase gene (FH) mutation, have been shown to be associated with the development of RCC." (PMID 37569676, 2023). "Cutaneous leiomyomatosis as well as renal cell cancer are additional important features suggesting FH mutation." (PMID 36773604, 2023). "Fumarate hydratase mutations can be found in a hereditary form of type 2 pRCC, in hereditary leiomyomatosis and in renal cell carcinoma." (PMID 35626699, 2022). "Mutations in protein subunits of succinate dehydrogenase (SDHA/SDHB/SDHC/SDHD and assembly factor SDHAF2) and fumarate hydratase (encoded by the single gene FH) lead to rare forms of renal cell carcinoma (RCC; denoted by SDHRCC and FHRCC, respectively)." (PMID 35288096, 2022). "HLRCC is an autosomal dominant disorder caused by mutations of the fumarate hydratase (FH) gene, characterized by cutaneous leiomyoma, and concomitant with multiple uterine leiomyomas and renal cell carcinoma." (PMID 36176479, 2022). "Fumarate hydratase (FH) - deficient renal cell carcinoma (FHdRCC) is a rare aggressive subtype of RCC caused by a germline or sporadic loss-of-function mutation in the FH gene." (PMID 35912170, 2022). "When FH is mutated, as described for instance in renal cell cancer (RCC) and kidney renal papillary cell carcinoma (KIRP), fumarate accumulates." (PMID 34065551, 2021). "Here, we report this germline FH c.914T > C (p.Phe305Ser) variant in two additional immunohistochemistry and molecularly proven FH‐deficient renal cell carcinoma cases, and demonstrate that the variant segregates with disease in a proband's family." (PMID 32463173, 2020). "The tumor displayed papillary, tubulocystic, and infiltrating tubular and solid growth patterns and showed prominent nucleoli and perinucleolar halos that were highly suspicious for FH‐deficient renal cell carcinoma." (PMID 32463173, 2020). "That case report was an individual with FH‐deficient renal cell carcinoma which was diagnosed before the age of 30." (PMID 32463173, 2020).
renal cell carcinoma (continued). "Of the 13,722 advanced patients (including 560 with renal cell carcinoma) who have consented for somatic and germline analysis, we have identified only two individuals with the FH c.914T > C (p.Phe305Ser) variant." (PMID 32463173, 2020). "Fumarate hydratase (FH) mutations are associated with aggressive papillary type 2 renal cell carcinoma termed FH-deficient renal cell carcinoma (FH-RCC)." (PMID 32197306, 2020). "For example, treatment with dimethylfumarate, a cell-permeable form of fumarate, strongly reduces invasion and metastasis formation in melanoma, although overexpression of FH in a FH-deficient renal cell carcinoma line inhibits cellular migration and invasion." (PMID 26812134, 2016). "Loss of fumarate hydratase (FH) function has been associated with the development of hereditary leiomyomas and renal cell carcinoma, whereas succinate dehydrogenase (SDH) mutations account for paragangliomas and pheochromocytomas." (PMID 26713093, 2015). "Fumarate hydratase (FH) mutations are associated with heritable predisposition to leiomyoma, leiomyosarcoma or renal cell carcinoma." (PMID 26056367, 2015). "Like SDH, FH is a tumor suppressor, and loss of heterozygosity will predispose FH mutant carriers to develop disorders including renal cell cancer, cutaneous and uterine leiomyomas, and encephalopathies." (PMID 26294907, 2015). "For example, mutations in the TCA enzyme, fumarate hydratase (FH) lead to hereditary leiomyomatosis (that causes cutaneous and uterine leiomyomas) and renal cell carcinoma (HLRCC) that causes type II papillary kidney cancer." (PMID 24124625, 2013). "Mutations in another TCA enzyme, fumarate hydratase (FH), cause cutaneous and uterine leiomyomas, as well as renal cell carcinomas." (PMID 16288567, 2005). "Leaving the excision site open after complete excision of this leiomyoma with FH-deficient morphology may decrease the risk of developing renal cell carcinoma." (PMID 41710846, 2026). "This case highlights potential links to the pathophysiology of how HLRCC-associated renal cell cancers may arise from FH-deficient leiomyomas around a decade later." (PMID 41710846, 2026). "Diagnosis: Fumarate hydratase-deficient renal cell carcinoma (FH-RCC)." (PMID 40678055, 2025). "Immunohistochemistry of tumour tissue proved FH-deficient renal cell cancer." (PMID 40264827, 2025). "Therefore, renal cell carcinomas caused by FH germline or somatic mutations have been collectively referred to as FH-deficient renal cell carcinomas in the new 2022 edition of the WHO renal tumor classification." (PMID 39659780, 2024). "Liver metastases also showed metastatic FH-deficient renal cell carcinoma." (PMID 39555225, 2024). "With increasing research experience, it has been recognized that the histological spectrum of FH-deficient renal cell carcinoma has expanded from high-grade to low-grade tumors, with occasional reports of synchronous and metachronous conventional high-grade morphology in low-grade forms." (PMID 39659780, 2024). "Final pathologic diagnosis: FH-deficient renal cell carcinoma (low grade)." (PMID 39659780, 2024). "FH is a housekeeping and tumor suppressor gene, and its germline inactivating mutations cause severe pathologies such as uterine and cutaneous leiomyomata and renal cell carcinoma." (PMID 38721148, 2024). "With further research, the 2022 edition of WHO proposed that a few cases of FH-deficient renal cell carcinoma are eosinophilic low-grade forms, but the description is relatively brief, and most of these rare form of tumors have a relatively favorable prognosis." (PMID 39659780, 2024). "Because of the well-established role of FH mutations in renal cancer risk, it was possible that the FH mutation could have led to the development of renal cell carcinoma in this case." (PMID 38873645, 2024). "Therefore, when diagnosed with FH-deficient renal cell carcinoma, timely surgical treatment should be performed to prevent the occurrence of metastatic cancer." (PMID 38974045, 2024).